SNHG12 (small nucleolar RNA host gene 12)
Diseases named in the same sentence as SNHG12 in open-access papers (continued):
Sharing a sentence is not in itself a finding about the gene and the disease.
ischemic stroke (6 papers, 2019 to 2024). A stroke disorder caused by obstruction of blood flow to the brain, due to thrombotic (local blood clot formation) or embolic (due to a blood clot or other material traveling from another site) event. "Increased LC3 II/I ratio and Beclin-1 and a decrease in p62 are indications that up-regulated SNHG12 induced autophagy activation and reduced cellular injury during ischemic stroke." (PMID 39021183, 2024). "SNHG12, an RNA gene that affiliated with the long non-coding RNA class, has been reported to be in connection with many disease occurrences, for instance, ischemic stroke." (PMID 33031264, 2020). "LncRNA small nucleolar RNA host gene 12 (SNHG12) accelerates angiogenesis following ischemic stroke via a miR-150/VEGF pathway, which further clarifies the mechanism of angiogenesis after ischemic stroke and provides a target for the treatment of this disease." (PMID 31680832, 2019). "Also, SNHG12's function as a regulator of mesenchymal stem cell (MSC) activity in ischemic stroke injury is established." (PMID 39021183, 2024). "Other studies have also reported that SNHG12 promotes angiogenesis during ischemic stroke." (PMID 38833118, 2024). "Infarct volume was reduced, and cell growth/angiogenesis was enhanced by up-regulated SNHG12, suggesting that SNHG12 could promote angiogenesis following ischemic stroke." (PMID 33613191, 2020). "Recent studies have identified several lncRNAs that modulate autophagy in ischemic stroke, including MALAT1, MIAT, SNHG12, H19, AC136007." (PMID 39021183, 2024).
nasopharyngeal carcinoma (6 papers, 2017 to 2022). A carcinoma arising from the nasopharyngeal epithelium. "SNHG12 was shown to be an effective diagnostic biomarker in nasopharyngeal carcinoma with a multivariate Cox regression analysis." (PMID 34372942, 2021). "In accordance, it has been previously determined that lncRNA SNHG12 serves as a negative predictor of clinicopathological characteristics and survival in renal cell, prostate, and nasopharyngeal carcinomas." (PMID 35658874, 2022).
liver cancer (5 papers, 2019 to 2026). An epithelial or non-epithelial malignant neoplasm that arises from the liver. "However, more evidence from tumor sphere formation assays and in vivo experiments is needed to clarify the specific role of SNHG12 in regulating the stemness of liver cancer cells." (PMID 41474641, 2026). "The lncRNAs small nucleolar RNA host gene 12 (SNHG12), induced by c-Myc, highly upregulated in liver cancer (HULC), HOX transcript antisense intergenic RNA (HOTAIR), and long intergenic non-protein-coding RNA-regulator of reprogramming (lincRNA-ROR) have altered expression in TNBC." (PMID 38473871, 2024). "Additionally, silencing SNHG12 decreases the expression of stem cell marker proteins (CD133, CD44, Nanog, LGR5, EpCAM) in liver cancer cells." (PMID 41474641, 2026).
pancreatic cancer (5 papers, 2020 to 2023). "CAPAN1 cells were selected and cultured for additional exploration of SNHG12 biological function in pancreatic cancer." (PMID 32432698, 2020). "Further investigation on SNHG12 specific function in pancreatic cancer was studied by transfecting corresponding si-RNAs (si-NC, si-SNHG12) into CAPAN1 cells, which identified that knockdown of SNHG12 suppressed pancreatic cancer cells growth by MTT assay." (PMID 32432698, 2020). "This research extrapolated that SNHG12 was a pivotal element in accelerating the progression of pancreatic cancer through augmenting proliferation, increasing migration and invasion." (PMID 32432698, 2020). "To further investigate the biological function of SNHG12 in cell invasion, we conducted transwell chamber assay and found that invasion rate of pancreatic cancer cells was proportional to the SNHG12 expression level." (PMID 32432698, 2020). "In this research, it is the first time to elaborate the precise pathological relation of SNHG12 and the progression of pancreatic cancer." (PMID 32432698, 2020). "Flow cytometry and transwell chamber assay were utilized to verify the promoting effects on proliferation and invasion that SNHG12 acts in pancreatic cancer cells." (PMID 32432698, 2020). "The results suggested that SNHG12 overexpression reduced mRNA expression of miR-320b in pancreatic cancer cells." (PMID 32432698, 2020). "Current data in the present study demonstrated that high expression of SNHG12 in pancreatic cancer accelerated the progress of cell growth and invasion." (PMID 32432698, 2020). "Luciferase activity assay certified that miR-320b is a target of SNHG12 in pancreatic cancer in the present study." (PMID 32432698, 2020). "We also studied the expression of SNHG12 in pancreatic cancer and its correlation with clinicopathological features of patients with pancreatic cancer." (PMID 32432698, 2020). "Further mechanism of SNHG12 depressing the progression of pancreatic cancer cells was studied and miR-320b was identified as a factor that was negative regulated by SNHG12." (PMID 32432698, 2020). "Here, we found lncRNA small nuclear RNA host gene 12 (SNHG12) is highly expressed in pancreatic cancer tissues and cell lines through qRT-PCR, which suggested that SNHG12 possibly accelerates the progression of pancreatic cancer." (PMID 32432698, 2020). "In order to figure out whether SNHG12 produces an effect by absorbing miR-320b, two pancreatic cancer cell lines (CAPAN1 and PANC1) with up-regulated SNHG12 were co-transfected with miR-320b mimic." (PMID 32432698, 2020). "The transcription level of SNHG12 was estimated in pancreatic cancer tissues and cell lines." (PMID 32432698, 2020). "The results showed a conspicuous increase of SNHG12 in pancreatic cancer tissues and cell lines." (PMID 32432698, 2020). "High SNHG12 expression level was first confirmed in pancreatic cancer tissues and cell lines using qRT-PCR, which suggested that SNHG12 could be invoked as a biomarker for early diagnosis of pancreatic cancer." (PMID 32432698, 2020). "It was unanimous to our hypothesis that the viability of SNHG12 silencing cells escalated at a lower rate than those with pLV-SNHG12 transfection, which might suggest that SNHG12 was functioned as a promoting factor in pancreatic cancer proliferation." (PMID 32432698, 2020). "LINC00462, LINC00958, SNHG12, and OIP5-AS1 are among lncRNAs whose roles in the progression of EMT have been validated in pancreatic cancer." (PMID 34827663, 2021). "Consequently, this research elucidated for the first time that SNHG12 is a novel candidate for early diagnosis biomarker and promising treatment target of pancreatic cancer, and SNHG12/miR-320b could be used as alternate therapeutic strategy for better rescuing patients with pancreatic cancer." (PMID 32432698, 2020).
pancreatic cancer (continued). "SNHG12 was significantly up-regulated in pancreatic cancer tissues and metastatic pancreatic cancer tissues versus normal tissues and non-metastatic pancreatic cancer tissues, respectively." (PMID 32432698, 2020).
bladder cancer (4 papers, 2016 to 2021). "Moreover, RNA sequencing data from the Cancer Cell Line Encyclopedia (CCLE) revealed higher expression of SNHG12 in the bladder cancer cell lines SW780 and UMUC3, compared to normal control cell lines." (PMID 31620362, 2019). "The increased expression of SNHG12 also correlated with shorter survival time of patients, suggesting that it may be utilized as a potential biomarker for the improved prognosis, and as a target for the treatment of bladder cancer." (PMID 31620362, 2019). "Jiang found that SNHG10, SNHG12, and LINC00115 were abnormally expressed in bladder cancer and that downregulation of SNHG12 expression was related to the inhibition of tumor proliferation." (PMID 34641864, 2021). "Depletion of SNHG12 in SW780 and UMUC3 cell lines by siRNA resulted in impaired cellular proliferation, colony formation, and invasion potential of bladder cancer cell lines." (PMID 31620362, 2019). "For example, we found that an L-FFL motif constituted by SNHG12, E2F1, and miR-16, and an M-FFL motif constituted by E2F1, miR-16 and AURKB could form a complex regulation motif by sharing common TF E2F1 and miRNA miR-16, which were highly dysregulated in breast and bladder cancers." (PMID 27322142, 2016).
colon cancer (4 papers, 2020 to 2025). "Similarly, SNHG12 overexpression exhibited a positive correlation with the progression of colon cancer." (PMID 38833118, 2024).
esophageal squamous cell carcinoma (3 papers, 2020 to 2025). Esophageal squamous cell carcinoma (ESCC) is a type of esophageal carcinoma (EC) that can affect any part of the esophagus, but is usually located in the upper or middle third. "In esophageal squamous cell carcinoma, SNHG12 regulates BMI1 expression via sponging miR‐6835‐3p and enhances CTNNB1 stability via recruiting IGF2BP2." (PMID 32239639, 2020).
papillary thyroid carcinoma (3 papers, 2019 to 2022). "Besides, it was also reported that SNHG12 facilitated papillary thyroid carcinoma cell migration and invasion partly by regulating Wnt/β-catenin pathway." (PMID 33294456, 2020).
Cerebral ischemia (2 papers, 2020 to 2022). Restriction of arterial blood supply to the brain associated with insufficient oxygenation to support the metabolic requirements of the tissue. "Additionally, the sponging of miR-30b and miR-30d by lncRNAs SNHG12 (small nucleolar RNA host gene 12) and C2dat2 (CAMK2D-associated transcript 2), respectively, was shown to increase autophagy and apoptosis after cerebral ischemia–reperfusion injury." (PMID 35204010, 2022).
clear cell renal cell carcinoma (2 papers, 2021 to 2022). "Small nucleolar RNA host gene 12 (SNHG12) has been indicated in the tumorigenesis of various human cancers, including clear cell renal cell carcinoma (ccRCC)." (PMID 33787057, 2021).
esophageal carcinoma (2 papers, 2020 to 2023). A primary or metastatic malignant neoplasm involving the esophagus. "In our research, we discovered that 3 lncRNAs from SNHG family (SNHG1, SNHG7, and SNHG12) were upregulated in ESCA (esophageal carcinoma) tissues based on Cancer RNA‐Seq Nexus analysis." (PMID 32239639, 2020). "Snhg12 can function in an RNA network comprised of lncRNA-miRNA-mRNA interactions, with the lncRNA serving as a miRNA sponge that regulates the target protein-coding mRNA; this ‘competing endogenous RNA’ or ‘ceRNA’ is protective in alcohol-induced esophageal carcinoma." (PMID 37987368, 2023).
fibroids (2 papers, 2024 to 2025). "The results showed that LINC02433, LINC01449, SNHG12, H19, and HOTTIP were elevated in premenopausal fibroids, but remained unchanged in postmenopausal ones, while ZEB2-AS1 displayed higher levels only in postmenopausal fibroids." (PMID 40862769, 2025).
gastric adenocarcinoma (2 papers, 2021). "It has been proved in a previous study that SNHG12 shows high expression in gastric adenocarcinoma, and the survival time of GC patients with high SNHG12 expression was markedly shorter than that of patients with low SNHG12 expression." (PMID 34656115, 2021). "The prediction results indicated that SNHG12 showed high expression in gastric adenocarcinoma cells and the survival time of GC patients with highly-expressed SNHG12 was remarkably shorter than that of patients with poorly-expressed SNHG12." (PMID 34656115, 2021).
lymphoma (2 papers, 2020 to 2021). A malignant (clonal) proliferation of B- lymphocytes or T- lymphocytes which involves the lymph nodes, bone marrow and/or extranodal sites. "Binding of MYC near the promoters of Snhg12, Mir17hg is readily detected and increases in B cells from the pre-lymphomatous and the fully malignant stage (lymphoma)." (PMID 33134177, 2020). "A positive correlation between MYC and Snhg12 was also seen in the Eμ-MYC transgenic lymphoma model adding support to the notion that Snhg12 might have important roles in other hematopoietic malignancies besides NKTCL." (PMID 33134177, 2020).
malignant glioma (2 papers, 2019 to 2020). A grade III or grade IV glioma arising from the central nervous system. "Another recently discovered MGMT-independent mechanism involves the long non-coding RNA small nucleolar RNA host gene 12 (SNHG12), which is highly expressed in malignant gliomas via epigenetic demethylation of its promoter." (PMID 33396284, 2020). "TDP-43 also plays an oncogenic role in malignant glioma cell progression by stabilizing small nucleolar RNA host gene 12 (SNHG12)." (PMID 31262091, 2019).
Obesity (2 papers, 2022 to 2025). Accumulation of substantial excess body fat. "Experimental overexpression of Snhg12 in mice with diet-induced obesity resulted in a significant reduction in inflammation in adipose tissue." (PMID 40869388, 2025). "Given that diabetes is a major risk factor for the development of PAD, progression of PAD, and major adverse limb events and cardiovascular events, we evaluated the role of Snhg12 silencing in a mouse model of obesity and diabetes." (PMID 34793334, 2022).
sarcoma (2 papers, 2020 to 2021). A usually aggressive malignant neoplasm of the soft tissue or bone. "Therefore, the interaction of SNHG12, miR-133a-3p/miR-133b and GNAI3 in sarcoma was worthwhile of exploration." (PMID 33653335, 2021). "Fourthly, the relationship of tumor histological grading and SNHG12 expression could not be tested for the lack of original data, like that carcinomas/epithelial or sarcomas/mesenchymal histogenesis were not mentioned in the included studies, which need further analysis in future study." (PMID 33031264, 2020).
thyroid cancer (2 papers, 2020 to 2025). "In thyroid cancer, multiple studies have confirmed the abnormal upregulation of SNHG12 and its close association with clinical malignant phenotypes." (PMID 41234719, 2025). "Related experiments validated that SNHG12’s promotion of malignant behavior in thyroid cancer cells primarily occurs through the miR-16-5p pathway." (PMID 41234719, 2025). "In summary, SNHG12 is widely overexpressed in thyroid cancer tissues and cells, promoting tumor cell proliferation, invasion, metastasis, and anti-apoptotic processes through multiple pathways." (PMID 41234719, 2025). "Given the well-established pivotal role of the Wnt/β-catenin pathway in the development and progression of multiple tumors, this finding suggests that SNHG12 may drive thyroid cancer progression through this pathway." (PMID 41234719, 2025). "Mechanistic studies indicate that SNHG12 regulates key molecules in the Wnt/β-catenin signaling pathway, including β-catenin, MMP-2, and Cyclin D1, thereby influencing invasion, metastasis, and proliferation in thyroid cancer cells." (PMID 41234719, 2025). "In thyroid carcinoma, certain SNHG family members (e.g., SNHG7, SNHG15, SNHG12, SNHG14) have been reported as oncogenes, while others (e.g., SNHG3, SNHG5) may function as tumor suppressors—a discrepancy warranting further investigation." (PMID 41234719, 2025).
/T-cell lymphoma (1 paper, 2024). "For example, c-MYC regulates the expression of the lncRNA small nucleolar RNA host gene 12 (SNHG12) to modulate cell proliferation as well as drug resistance in natural killer/T-cell lymphoma." (PMID 38886753, 2024).
depression (1 paper, 2022). "In addition, the expression levels of KCNN4, MOG, and SNHG12 genes can influence inflammatory factors, which may affect grip strength and depression by influencing the inflammatory response." (PMID 36520780, 2022).
diabetes (1 paper, 2022). "Snhg12 knockdown in a model of diabetes leads to impaired blood flow recovery after FAL." (PMID 34793334, 2022).
inflammatory skin disease (1 paper, 2023). Inflammatory skin disorders covers a broad category that includes many conditions ranging in severity, from mild itching to grave medical health complications These disorders are common in people of all ages and races. "Additionally, EPHA1-AS1, CYP4Z2P and SNHG12 gene upregulation have all been previously linked to inflammatory skin diseases." (PMID 38003532, 2023).
intrahepatic cholangiocarcinoma (1 paper, 2021). A carcinoma that arises from the intrahepatic bile duct epithelium in any site of the intrahepatic biliary tree. "Our study aimed to explore the functions of SNHG12 on intrahepatic cholangiocarcinoma (ICC) progression and its interaction with miR-199a-5p and Klotho." (PMID 34239888, 2021).
ischemia (1 paper, 2022). A hypoperfusion of the BLOOD through an organ or tissue caused by a PATHOLOGIC CONSTRICTION or obstruction of its BLOOD VESSELS, or an absence of BLOOD CIRCULATION. "Together, these findings indicate that SNHG12 plays an important role in the angiogenic EC response to ischemia." (PMID 34793334, 2022). "Together, these data suggest that SNHG12 plays a role in EC angiogenesis that is not caused by increased monocyte migration or differential macrophage polarization that modulates the inflammatory phenotype in the wound healing response to ischemia." (PMID 34793334, 2022).
laryngeal carcinoma (1 paper, 2021). Carcinoma that arises from the laryngeal epithelium. "This study suggested that WWP1 was regulated by SNHG12/miR-129-5p axis in laryngeal cancer." (PMID 34226507, 2021). "LncRNA SNGH12 (small nucleolar RNA host gene 12) elevated cell proliferation and invasiveness via acting as a sponger of miR-129-5p and subsequent upregulation of WWP1 in laryngeal cancer cells." (PMID 34226507, 2021).
limb ischemia (1 paper, 2022). A ischemia that involves the limb. "In order to determine the role of SNHG12 after limb ischemia, anesthetized mice were subjected to FAL." (PMID 34793334, 2022). "Knockdown of SNHG12 in mice undergoing femoral artery ligation (FAL) as a model for limb ischemia shows that there are decreased arterial number and arterial size, suggesting decreased angiogenesis in vivo." (PMID 34793334, 2022). "Knockdown of Snhg12 in vivo in C57BL/6 and BALB/c mice decreases blood flow recovery after acute limb ischemia." (PMID 34793334, 2022).
liver cirrhosis (1 paper, 2017). "However, SNHG12 expression was not correlated with other clinicopathological variables such as gender, age, serum AFP, liver cirrhosis, PVTT and differentiation (P > 0.05)." (PMID 28073380, 2017).